DMD (dystrophin)
Diseases named in the same sentence as DMD in open-access papers (continued):
Sharing a sentence is not in itself a finding about the gene and the disease.
Duchenne muscular dystrophy (continued). "Our experiments are, to our knowledge, the first to demonstrate the feasibility and efficacy of direct protein replacement to combat the effects of dystrophin deficiency in mdx mice, an established model of Duchenne muscular dystrophy in humans." (PMID 19478831, 2009). "In vivo, MLN-273 halts the degradation of dystrophin and dystrophin-associated proteins in a mouse model of Duchenne muscular dystrophy." (PMID 19924240, 2009). "The loss of dystrophin compromises muscle cell membrane stability and causes Duchenne muscular dystrophy and/or various forms of cardiomyopathy." (PMID 19478831, 2009). "The mdx mouse – a Duchenne muscular dystrophy model – was produced by introducing a point mutation in the dystrophin gene." (PMID 18489762, 2008). "Encouraging results for this exon skipping technique have been reported in a Duchenne muscular dystrophy mouse model with a nonsense mutation in exon 23 of the dystrophin gene." (PMID 19787084, 2008). "Targeted exon skipping of selected exons in the dystrophin gene transcript can remove nonsense or frame-shifting mutations that would otherwise have lead to Duchenne Muscular Dystrophy, the most common childhood form of muscle wasting." (PMID 17601349, 2007). "Duchenne muscular dystrophy results from mutation of the dystrophin gene, causing skeletal and cardiac muscle loss of function." (PMID 17626629, 2007). "Mutations in the very large dystrophin gene (2.4 million bases) are associated with both Duchenne muscular dystrophy (DMD), characterized by severe and progressive muscle degeneration, and the milder Becker muscular dystrophy (BMD)." (PMID 17487273, 2007). "For example, deletion of the C. elegans dystrophin gene, the homolog of a gene involved in Duchenne's Muscular Dystrophy, in combination with a second mutation in the myogenic factor MyoD leads to progressive muscle degeneration." (PMID 17551584, 2007). "The mdx mouse model of Duchenne muscular dystrophy is widely utilized to evaluate the potential of therapeutic regimens to modulate the loss of skeletal muscle function associated with dystrophin mutation." (PMID 17626629, 2007). "Protein-truncating mutations in the dystrophin gene typically lead to Duchenne muscular dystrophy (DMD), the most common severe childhood form of muscle wasting (review,)." (PMID 17601349, 2007). "Dystrophin, identified nearly 20 years ago as the protein deficient in Duchenne muscular dystrophy (DMD), is now recognised as the founder member of a protein superfamily with representatives throughout the animal kingdom." (PMID 17233888, 2007). "The mdx mouse, the most widely used animal model for Duchenne muscular dystrophy, carries an ochre nonsense mutation in dystrophin exon 23 that drastically reduces the abundance of dystrophin mRNA and consequently abolishes dystrophin expression." (PMID 17487273, 2007). "Duchenne muscular dystrophy is a fatal genetic disorder caused by dystrophin gene mutations that result in premature termination of translation and the absence of functional protein." (PMID 16719929, 2006). "BACKGROUND: In addition to progressive muscle wasting, one-third of patients with Duchenne muscular dystrophy (DMD) exhibit varying degrees of cognitive impairment, which are associated with mutations of the DMD gene within the region coding for dystrophins Dp71 and Dp40." (PMID 41824108, 2026). "For example, it may play a role in the pathogenesis of Duchenne muscular dystrophy (DMD), a progressive, genetic (X-linked recessive) neuromuscular disorder caused by mutations in the DMD gene." (PMID 41191311, 2026). "The proband harbored a de novo hemizygous DMD frameshift variant consistent with Duchenne muscular dystrophy, a paternally inherited heterozygous GJA1 in-frame indel associated with oculodentodigital dysplasia (ODDD), and a novel homozygous FYCO1 nonsense variant causing congenital cataract." (PMID 41853139, 2026).
Duchenne muscular dystrophy (continued). "Duchenne muscular dystrophy (DMD) is an X-linked disorder caused by mutations in the dystrophin (DMD) gene, characterized by progressive muscle strength decline, leading to loss of independent mobility during adolescence, along with respiratory insufficiency and dilated cardiomyopathy." (PMID 40325330, 2025). "Duchenne muscular dystrophy (DMD) is an X-linked recessive disorder caused by loss-of-function mutations in the DMD gene that encodes dystrophin; DMD manifests as progressive multisystem muscular degeneration with a predilection for skeletal, diaphragmatic, and cardiac tissues." (PMID 40134720, 2025). "DMD is inactivated in females, and mutations in the gene can cause Duchenne muscular dystrophy." (PMID 39633006, 2025). "Duchenne muscular dystrophy (DMD) is a severe X-linked neuromuscular disorder primarily characterized by progressive degeneration of skeletal and cardiac muscle due to mutations in the DMD gene, which encodes dystrophin proteins." (PMID 41431697, 2025). "A study demonstrated that the combined inhibition of ActRIIb and exon skipping for dystrophin using an adeno-associated vector enhanced the tetanic and specific forces in the mdx mouse model for Duchenne muscular dystrophy, indicating a potential therapeutic strategy for muscle wasting diseases." (PMID 39982358, 2025). "Males with Duchenne muscular dystrophy aged 5 years to 18 years were subdivided according to the predicted effects of the participants' DMD mutation on dystrophin isoform expression (group 1, Dp427 absent, Dp140/Dp71 present; group 2, Dp427/Dp140 absent, Dp71 present)." (PMID 40084496, 2025). "Duchenne muscular dystrophy is caused by loss of the dystrophin protein." (PMID 38540736, 2024). "Duchenne Muscular Dystrophy (DMD) is a lethal disease caused by mutation in the dystrophin gene." (PMID 38540201, 2024). "Duchenne muscular dystrophy (DMD) results from mutations in the DMD." (PMID 39009678, 2024). "Mutations in the DMD gene cause fatal Duchenne Muscular Dystrophy (DMD)." (PMID 38891104, 2024). "This miRNA cluster is highly conserved among placental mammals and is known to be regulated by a maternally imprinted DLK1-DIO3 region, which has been associated with severe muscle disease, which is caused by the impaired expression of dystrophin called Duchenne muscular dystrophy." (PMID 38891641, 2024). "It further added that a fusion transcript was detected, PFKFB3::DMD, with reads spanning exon 1 of PFKFB3 to exon 45 of DMD, providing even more conclusive evidence that the 306 kb inverted insertion of 10p15.1 is the pathogenic variant that results in Duchenne muscular dystrophy in both boys." (PMID 39595988, 2024). "In addition, Elevidys, an AAVrh74-based therapy, was approved by the FDA for the treatment of Duchenne muscular dystrophy (DMD) resulting from mutations in the DMD gene, following i.v. administration." (PMID 39559557, 2024). "Traditional genetic analysis is best suited to diagnose monogenic conditions, such as Duchenne muscular dystrophy (Duchenne MD), resulting from dystrophin mutations, or cystic fibrosis, which is caused by cystic fibrosis transmembrane conductance regulator (CFTR) mutations." (PMID 39376536, 2024). "One of the important consequences of Duchenne muscular dystrophy and the loss of dystrophin protein in striated muscles is the disruption of the integrity of the membranes of muscle fibers and cells (in the case of cardiomyocytes) and the dysregulation of ion homeostasis." (PMID 39337383, 2024). "Furthermore, various genes encoding cardiac cytoskeletal proteins such as dystrophin (DMD) for Duchenne muscular dystrophy, sarcoglycan (SGC) for sarcolemmal instability muscular dystrophy, and filamin C (FLNC) are associated with arrhythmias and SCD." (PMID 38666937, 2024).
Duchenne muscular dystrophy (continued). "Principally expressed in skeletal muscle, the dystrophin protein product protects the muscle sarcolemma against contraction-induced injury, and dystrophin deficiency results in the fatal muscle-wasting disease, Duchenne muscular dystrophy." (PMID 37509720, 2023). "Dystrophin mutations lead to Duchenne muscular dystrophy, an X-linked recessive disorder." (PMID 36928364, 2023). "DMD gene pathogenic variations cause a spectrum of phenotypes, ranging from severe Duchenne muscular dystrophy, the Becker milder cases, the intermediate or very mild muscle phenotypes invariably characterized by high CK, and the ultrarare fully-asymptomatic cases." (PMID 38288333, 2023). "Mutations in the DMD gene that abolish production of functional dystrophin protein cause Duchenne muscular dystrophy (DMD), which manifests as progressive muscle wasting and loss of muscle function starting in young boys and leads to premature death, generally in the 3rd or 4th decade of life." (PMID 37667454, 2023). "Interestingly, a DMD nonsense variant causing Duchenne-type muscular dystrophy in a Maine Coon family was just reported." (PMID 36834603, 2023). "In the last two decades, antisense oligonucleotides (AONs) that induce corrective exon skipping have matured as promising therapies aimed at tackling the dystrophin deficiency that underlies the severe and progressive muscle fiber degeneration in Duchenne muscular dystrophy (DMD) patients." (PMID 37036788, 2023). "Therefore, this technique using HAC gives insight into developing new treatments and novel humanized Duchenne muscular dystrophy mouse models with human dystrophin gene mutations." (PMID 36928364, 2023). "Duchenne muscular dystrophy (DMD) is caused by DMD mutations leading to dystrophin loss." (PMID 35083887, 2022). "Pathogenic variants in the DMD gene are responsible for Duchenne muscular dystrophy (DMD)." (PMID 35886062, 2022). "These myopathies are due to mutations in several genes, including dystrophin (Duchenne muscular dystrophy, DMD), calpain-3 (Limb girdle muscular dystrophies, LGMD2A), or titin [muscular dystrophy with myositis (MDM); tibial muscular dystrophy (TMD) and limb-girdle muscular dystrophy 2J (LGMD2J)]." (PMID 35846001, 2022). "Duchenne muscular dystrophy (DMD) is a severe neuromuscular disease arising from loss-of-function mutations in the dystrophin gene and characterized by progressive muscle degeneration, respiratory insufficiency, cardiac failure, and premature death by the age of thirty." (PMID 36230926, 2022). "Duchenne muscular dystrophy is a severe muscle-wasting disease caused by mutations in the DMD gene." (PMID 36320324, 2022). "Duchenne muscular dystrophy (DMD) is a muscle wasting disorder caused by mutations in the DMD gene." (PMID 35615709, 2022). "Duchenne muscular dystrophy (MIM #310200) is commonly caused by CNVs in the DMD gene." (PMID 35628876, 2022). "Duchenne muscular dystrophy (DMD) is a fatal X-linked recessive disease caused by an inability to produce functional dystrophin, a protein critical for muscular strength and stability, and the absence of which results in progressive muscular deterioration and fibrosis." (PMID 35205302, 2022). "Especially the diaphragm muscle is severely affected in mdx-type mice and exhibits progressive fiber degeneration and reactive myofibrosis making the dystrophin-deficient diaphragm a suitable tissue for studying the molecular and cellular pathogenesis of Duchenne muscular dystrophy." (PMID 36362832, 2022). "Treg cells were highly accumulated in skeletal muscles of mdx dystrophin-deficient mice, a model of human Duchenne muscular dystrophy (DMD), in which muscle injury and inflammation is mitigated by expansion of the Treg population but exacerbated by Treg-cell depletion." (PMID 35359918, 2022).
Duchenne muscular dystrophy (continued). "Duchenne muscular dystrophy phenotype variability is influenced by standards of care, therapy with glucocorticoid corticosteroids (GCs), and the genetic architecture of the patient, including the type and location of DMD mutations and genetic modifiers." (PMID 36011296, 2022). "In Duchenne muscular dystrophy, alterations in the expression of members of the dystrophin network are closely related to key pathophysiological features in dystrophin-deficient muscles, including degeneration-regeneration cycles, progressive fiber degeneration, fibrosis and chronic inflammation." (PMID 33540575, 2021). "Duchenne muscular dystrophy is caused by the mutations in the DMD gene." (PMID 34490244, 2021). "Based on the presence of Duchenne muscular dystrophy, glycerol kinase deficiency and probable congenital adrenal hypoplasia along with genetic confirmation of deletions involving dystrophin and glycerol kinase genes, the diagnosis of Xp21 contiguous gene deletion syndrome was made." (PMID 34689766, 2021). "Duchenne muscular dystrophy (DMD) is caused by >200 mutations in the gene encoding dystrophin, a protein that connects the cytoskeleton to the extracellular matrix, with a prevalence of 1:5,000 boys, DMD patients exhibit early and progressive skeletal muscle degeneration and weakness." (PMID 34019816, 2021). "Pathogenic variations in the dystrophin gene underlie Duchenne muscular dystrophy." (PMID 34502190, 2021). "Some, such as Duchenne muscular dystrophy and limb girdle muscular dystrophy 2H, are caused by mutations in genes encoding muscle structural proteins (dystrophin and Trim32, respectively), while others, like myotonic dystrophy, are caused by defects in RNA metabolism." (PMID 33561245, 2021). "Since dystrophin has been strongly associated with epilepsy in patients with Duchenne muscular dystrophy, it might be important in the epileptogenic process." (PMID 34877936, 2021). "The mdx mouse, which lacks dystrophin protein due to a mutation that results in a premature stop codon in exon 23, is widely used as a mouse model for studying chronic muscle injury and pathophysiology of Duchenne muscular dystrophy." (PMID 34812145, 2021). "Duchenne muscular dystrophy, a genetic myopathy with the highest prevalence of 7.1 in 100,000 male births, is a fatal X-linked disorder caused by mutations in the dystrophin gene." (PMID 34778273, 2021). "These alterations in the cellular homeostasis may serve as mechanisms to compensate for deficits induced by the dystrophin loss in this model of Duchenne muscular dystrophy." (PMID 34206383, 2021). "Animal models of Duchenne muscular dystrophy have been instrumental for studying the molecular and cellular details of progressive degeneration in dystrophin-deficient muscle tissues, as well as testing of novel experimental treatment strategies to counteract the dystrophic phenotype." (PMID 32916630, 2020). "Interestingly, the activation of PPARβ/δ ameliorates the human Duchenne muscular dystrophy (DMD) phenotype in X-linked muscular dystrophy (mdx) mice that have a spontaneous mutation in the dystrophin gene." (PMID 33137899, 2020). "Additionally, several studies show the benefits of NAC as a potential therapeutic treatment for Duchenne muscular dystrophy, using dystrophic dystrophin-deficient mdx mice." (PMID 32197453, 2020). "Dystrophin-null sapje zebrafish is an excellent model for better understanding the pathological mechanisms underlying Duchenne muscular dystrophy, and it has recently arisen as a powerful tool for high-throughput screening of therapeutic candidates for this disease." (PMID 33057138, 2020). "Duchenne muscular dystrophy is caused by deficiency in expression of the dystrophin." (PMID 33228026, 2020). "Mutation in the dystrophin leads to Duchenne muscular dystrophy (DMD)." (PMID 33228026, 2020).
Duchenne muscular dystrophy (continued). "In male patients, a nonsense or frameshift mutation in the DMD gene cause a severe phenotype, Duchenne muscular dystrophy (DMD; OMIM 310,200), while in-frame deletion/duplication or missense mutation result in a milder phenotype, Becker muscular dystrophy (BMD; OMIM 300,376)." (PMID 31919629, 2020). "Duchenne Muscular Dystrophy (DMD) is a rare disorder caused by mutations in the dystrophin gene." (PMID 32503598, 2020). "As a control, we compared the burrowing strength of fzo-1 mutants to dys-1(eg33) animals, which lack the functional orthologue of the dystrophin protein that is implicated in Duchenne muscular dystrophy and previously shown to be highly defective in the burrowing assay." (PMID 30840087, 2019). "Duchenne muscular dystrophy originates from mutations in the dystrophin gene." (PMID 31861214, 2019). "Furthermore, mutations in Dystrophin lead to deficits in stem cell self-renewal indicating that Duchenne muscular dystrophy is also a stem cell disease." (PMID 31754462, 2019). "Duchenne muscular dystrophy (Duchenne) is caused by pathogenic variants in the DMD gene." (PMID 30450799, 2019). "In mdx mice, a model for Duchenne muscular dystrophy exhibiting a point mutation of the dystrophin gene, muscular S1PL expression is higher compared to control muscles, while S1P plasma level is reduced Upregulation of S1P by THI increases regeneration and muscle force in mdx mice." (PMID 31861214, 2019). "Similar strategies have also been employed for Duchenne Muscular dystrophy, an X-linked neuromuscular disorder that affects 1:5000 newborn boys, and is primarily caused by deletions, frameshift or nonsense mutations in the dystrophin (DMD) gene." (PMID 30906315, 2019). "Indeed, the loss of dystrophin protein expression causes the muscle wasting disease, Duchenne muscular dystrophy (DMD)." (PMID 30349485, 2018). "Furthermore, mitochondria fragmentation has also been involved in muscle degeneration in a model of Duchenne muscular dystrophy in C. elegans, which combines mutations of both hlh‐1/myoD and dys‐1/dystrophin." (PMID 29314608, 2018). "The dystrophin-deficient mdx mouse is the most common animal model for Duchenne muscular dystrophy." (PMID 29900212, 2018). "Duchenne muscular dystrophy (DMD) is a muscle wasting disease in boys due to loss of dystrophin." (PMID 29508262, 2018). "To test this hypothesis, we investigated potential IK1 abnormalities in dystrophin-deficient ventricular cardiomyocytes derived from the hearts of Duchenne muscular dystrophy mouse models." (PMID 27560040, 2017). "Considering that inhibition of miR-21 expression reduced fibrosis in the mildly affected dystrophin-deficient mdx mouse model of Duchenne muscular dystrophy, we next investigated if removal of miR-21 would have propitious effects in the milder LAMA2-CMD dy2J/dy2J mouse model." (PMID 28771630, 2017). "Duchenne muscular dystrophy is an X-linked genetic disease due to mutations in the dystrophin gene, leading to alterations in intracellular signaling that causes an imbalance between protein synthesis and protein degradation, with subsequent necrosis and fibrosis." (PMID 28845212, 2017). "Efficacy and versatility of this pipeline was exemplified by producing different CRISPR/Cas9-HCAdV targeting the human papillomavirus (HPV) 18 oncogene E6, the dystrophin gene causing Duchenne muscular dystrophy (DMD) and the HIV co-receptor C-C chemokine receptor type 5 (CCR5)." (PMID 29215041, 2017). "Duchenne muscular dystrophy is caused by mutations in the DYSTROPHIN gene." (PMID 27676442, 2016). "The fact that the Dp427-M isoform of dystrophin was identified as the most significant change in total muscle extracts from the mdx4cv model of dystrophinopathy perfectly agrees with the idea that the deficiency in dystrophin is the primary abnormality in Duchenne muscular dystrophy." (PMID 26793286, 2016).